SKP2 (S-phase kinase associated protein 2)
Diseases named in the same sentence as SKP2 in open-access papers (continued):
Sharing a sentence is not in itself a finding about the gene and the disease.
prostate carcinoma (continued). "Coexpression of Skp2 and Slug was confirmed in prostate cancer tissues by multiplex immunohistochemistry and confocal microscopy." (PMID 33799604, 2021). "Androgen regulation of Skp2 was also reported by others in LNCaP and C4-2 cells; however, Skp2 can also promote prostate cancer independently of the androgen receptor." (PMID 33799604, 2021). "Skp2 is overexpressed in multiple types of tumors, including hepatocellular carcinoma, prostate cancer, and glioblastoma, and is related to cancer proliferation, invasion, and metastasis." (PMID 34572430, 2021). "Significantly increased expression of Skp2, AR, and Slug, along with lower expression of E-cadherin, was also observed in primary prostate cancer in patients who already had lymph node metastases." (PMID 33799604, 2021). "SKP2 has been shown to also affect AR ubiquitination, but additionally its targets in prostate cancer include EZH2, p27, JARID1B, DAB2IP, AKT, BRCA2, ATF4, p27, p21, and Twist to regulate various cellular processes." (PMID 33572160, 2021). "Recent studies reported that overexpressed Skp2 was found in paclitaxel-resistant prostate cancer cells, and knockdown of Skp2 restored the sensitivity of paclitaxel in prostate cancer cells." (PMID 33841154, 2021). "In this study, significantly increased expression of Skp2, AR, and Slug, along with E-cadherin downregulation, was observed in primary prostate cancer in patients who already had lymph node metastases." (PMID 33799604, 2021). "In a previous study, we showed that androgen depletion decreased prostate cancer cell proliferation, in part through downregulation of Skp2." (PMID 33799604, 2021). "We have already reported that high Skp2 expression is associated with a mesenchymal phenotype and increased tumorigenic potential of DU145 prostate cancer cells." (PMID 33799604, 2021). "A more profound correlation between Slug and Skp2 in aggressive prostate cancer prompted us to perform dual staining in several prostate cancer tissues." (PMID 33799604, 2021). "Coregulation of Skp2 and Slug was also observed in docetaxel-resistant prostate cancer cells and a mouse mesenchymal subline." (PMID 33799604, 2021). "Skp2 overexpression has been observed in various tumor types, including prostate cancer, and it is related to tumor progression and metastatic disease." (PMID 33799604, 2021). "Enhanced expression of Skp2 had been repeatedly found in aggressive prostate cancer, which was also reproduced in our study." (PMID 33799604, 2021). "In our work, we confirmed an elevation of Skp2 in a cohort of patients with advanced prostate cancer and observed its correlation and coexpression with Slug." (PMID 33799604, 2021). "Among the most prominent E3 ligases that influence prostate cancer is SKP2, an F-box protein, and a crucial component of the SCF type of E3 ubiquitin ligase complexes." (PMID 33572160, 2021). "Selenonucleoside LJ-2618 was shown to be able to trigger G2/M cell cycle arrest in prostate cancer cells by promoting Skp2 degradation." (PMID 32165861, 2020). "To confirm the role of Skp2 in prostate cancer progression, we performed a retrospective analysis of Skp2 expression in patients with benign hyperplasia and prostate carcinoma." (PMID 30952903, 2019). "We found that the mesenchymal phenotype of prostate cancer cells was accompanied by an increase in Skp2 levels in all selected pairs of cell lines." (PMID 30952903, 2019). "Our results suggest that the high expression of CD24 is linked to the epithelial and less aggressive phenotype of metastatic prostate cancer cells, accompanied by the low expression of Skp2." (PMID 30952903, 2019).
prostate carcinoma (continued). "To assess the connection between Skp2 expression and a mesenchymal phenotype in prostate cancer cells, we employed three sets of prostate epithelial cell lines and their mesenchymal counterparts." (PMID 30952903, 2019). "Our results confirmed that Skp2 expression was increased in mesenchymal prostate cancer cells compared to their epithelial counterparts." (PMID 30952903, 2019). "To further assess the role of Skp2 in the tumorigenesis of the prostate cancer stem-like cells, we employed DU 145 cells in which SKP2 had been knocked down." (PMID 30952903, 2019). "As a result, SKP2 is up-regulated in several human cancers, including colorectal cancer, bladder cancer, BC, melanoma, prostate cancer, hepatocellular cancer, cervical cancer, and lymphoma." (PMID 30341246, 2019). "Our results show that the nuclear expression of Skp2 was significantly increased in prostate cancer tissues compared to benign hyperplasia tissues." (PMID 30952903, 2019). "Skp2 is a crucial component of SCFSkp2 E3 ubiquitin ligase and is often overexpressed in various types of cancer, including prostate cancer (PCa)." (PMID 30952903, 2019). "Herein, we show an association between elevated Skp2 levels and an EMT phenotype in patients with prostate cancer as well as in prostate cancer cell lines." (PMID 30952903, 2019). "LXRs ligands on prostate cancer reported an effect on cell proliferation and cell cycle, acting on p27 and SKP2." (PMID 29871693, 2018). "The LNCaP-SKP2 line was derived by stably overexpressing the SKP2 subunit of the CRL1SKP2 ubiquitin ligase in human LNCaP prostate cancer cells." (PMID 29861853, 2018). "For example, in both DRIVE and Achilles data sets, we noted that Rb-defective TCLs derived from prostate cancer, osteosarcoma, liver cancer and oesophageal cancer, exhibited sensitivity to SKP2 shRNA." (PMID 29915391, 2018). "Skp2 is overexpressed in human prostate cancers, which exerts critical downstream effects on STAT3 in human prostate cancer." (PMID 28157698, 2017). "Skp2 has been considered as a proto-oncogene and its overexpression is frequently observed in many cancers including prostate cancer." (PMID 26497688, 2015). "In this study, we found that p27 levels were elevated while Skp2 levels diminished in quiescent prostate cancer cells." (PMID 26416244, 2015). "Recent studies have found that miR-34a represses RhoA, a regulator of cell migration and invasion, by suppressing c-Myc–Skp2–Miz1 transcriptional complex that activates RhoA in human prostate cancer cells." (PMID 26077733, 2015). "In prostate cancer, the reciprocal regulation between DAB2IP and Skp2 can impact on the growth of prostate cancer cells." (PMID 26336990, 2015). "We therefore determined the expression of p27 and its regulatory proteins CRM1, Skp2 and Pirh2 during cell cycle re-entry by quiescent prostate cancer cells." (PMID 26416244, 2015). "Skp2 interacts with pRb, Pten, androgen receptor (AR), and H-Ras in prostate cancer, and serves as a critical converging point for these genes in regulation of senescence." (PMID 26497688, 2015). "Skp2 is strongly expressed in the hyperplastic/dysplastic and prostate carcinoma regions in the TRAMP model in our study." (PMID 26497688, 2015). "Our findings therefore provide evidence that FKA is a promising NEDDylation inhibitor for targeting Skp2 degradation in prostate cancer prevention and treatment." (PMID 26497688, 2015). "Immunohistochemical study exhibited an inverse correlation between DAB2IP and Skp2 protein expression in the prostate cancer tissue microarray." (PMID 25115390, 2014). "Skp2 can regulate several cellular functions responsible for prostate cancer progression, including cell cycle progress, signal transduction, or DNA repair." (PMID 25115390, 2014). "It has been reported that androgen depletion induces senescence in prostate cancer cells via down-regulation of Skp2." (PMID 24244503, 2013).
prostate carcinoma (continued). "Our LNCaP-S14 cell line, which was generated for the high-content screen that identified SMIP004, was derived by stably overexpressing the SKP2 subunit of the CRL1SKP2 ubiquitin ligase in human LNCaP prostate cancer cells." (PMID 23902736, 2013). "Western blotting experiments also showed that the protein levels of Akt1, phospho-Akt Ser473, phospho-Akt Thr308, PDK1, c-Myc, Skp2 in prostate cancer cells was decreased by triol treatment." (PMID 23785446, 2013). "For instance, the expression of Skp2 in prostate cancers is decreased by androgens and is mediated via pathways that are dependent on p107 as well as pathways that are independent of p107." (PMID 23087899, 2012). "In transgenic mouse models, SKP2 cooperates with N-Ras to drive lymphomagenesis, and tissue targeted expression of SKP2 results in hyperplasia, dysplasia, and low-grade carcinoma of the prostate gland." (PMID 23226679, 2012). "Consistent with Skp2’s role as a downstream effector of androgen receptor in mediating proliferation in prostate cancer cells, its expression level in androgen-responsive LNCaP cells is substantially higher than in androgen-independent PC-3 and DU-145 cells." (PMID 23071779, 2012). "In this study, we report a novel mechanism by which CG-12, a novel energy restriction-mimetic agent (ERMA), down-regulates the expression of Skp2 in prostate cancer cells." (PMID 23071779, 2012). "We developed a cell-based assay for measuring the levels of endogenous nuclear p27 in a high throughput screening format employing LNCaP prostate cancer cells engineered to overexpress SKP2." (PMID 21182779, 2010). "It is well documented that cytoplasmic Skp2 is frequently observed in more advanced breast and prostate cancer." (PMID 19549334, 2009). "SKP2 is sparsely overexpressed in human prostate hyperplasia, PIN and prostate adenocarcinoma compared to prostate normal tissues; Higher levels of SKP2 mRNA in prostate tumor tissues are associated with poorer survival of prostate cancer patients." (PMID 41542047, 2026). "In clinical studies of prostate cancer, SKP2 has been reported to be a key amplified gene." (PMID 41542047, 2026). "Therefore, Targeting SKP2 in both cancer cells and tumor microenvironment would be an excellent strategy in prostate cancer prevention and treatment." (PMID 41542047, 2026). "However, direct in vivo evidence for SKP2 on cancer initiation and prostatic microenvironment is still lacking and a SKP2 humanized mouse model is critical for developing prostate cancer immunoprevention approaches through targeting SKP2." (PMID 41542047, 2026). "In prostate cancer, high expression of SKP2 leads to IDH1 degradation." (PMID 40534867, 2025). "SKP2 knockdown and/or inhibition sensitized the paclitaxel resistance prostate cancer cells, suggesting that SKP2 inhibitors might be the potential drugs against SKP2 upregulated cancers." (PMID 38559562, 2024). "Since the miR-34a is downregulated in prostate cancer, overexpressing miR-34a downregulates RhoA and suppresses the c-Myc-SKP2 -Miz1 transcriptional assembly complex c-Myc-pTEFB complex that elongates transcription of numerous genes and affects the cellular function." (PMID 38559562, 2024). "Inactivating SKP2 inhibits the initiation of prostate cancer via ubiquitination of JARID1B." (PMID 36202787, 2022). "Novel treatment strategies targeting Skp2 and Slug by the neddylation blockade may be promising in advanced prostate cancer, as recently documented for other aggressive solid tumors." (PMID 33799604, 2021). "Novel treatment strategies targeting Skp2 and Slug by neddylation blockade may be promising in advanced prostate cancer, as recently documented for other aggressive solid tumors." (PMID 33799604, 2021). "A novel selenonucleoside (4′-selenofuranosyl-2, 6-dichloropurine, LJ-2618) may bear results in overcoming paclitaxel resistance by promoting Skp2 degradation and stabilizing p27 expression in paclitaxel-resistant prostate cancer." (PMID 34068643, 2021).
prostate carcinoma (continued). "Collectively, we report the coexpression of Skp2 and Slug in aggressive prostate cancer cells which can be inhibited by neddylation blockade, a potentially promising therapeutic approach for advanced prostate cancer." (PMID 33799604, 2021). "Besides, natural products such as curcumin, quercetin, lycopene, silibinin, EGCG and vitamin D can inhibit the expression of SKP2 in breast and prostate cancer 188-190." (PMID 32226545, 2020). "Skp2 has shown important roles in the development and progression of tumors as it was found to be frequently overexpressed in various human malignancies like hepatocellular carcinoma, breast cancer, lung cancers, prostate cancer, and osteosarcoma." (PMID 32165861, 2020). "Although Twist protein was not affected by Mint3 depletion in AsPC-1 cells, Mint3-mediated SKP2 expression may control the stability of Slug protein in the same fashion as Twist protein in prostate cancer." (PMID 32826949, 2020). "Although the impact of the differential expression of SKP2 between QNBC and TNBC remains unclear, AR was identified as an upstream regulator of SKP2 in prostate cancer cells." (PMID 33213491, 2020). "SKP2 inactivates KDM5B through ubiquitination in prostate cancer cells." (PMID 31776402, 2019). "Similarly, a novel selenonucleoside, LJ-2618, targeted Skp2 degradation and suppressed tumor growth in paclitaxel-resistant prostate cancer." (PMID 30847385, 2019). "As Skp2 overexpression has been correlated with poor prognosis in prostate cancer patients, we wanted to reveal whether high CD24 expression would be associated with a better prognosis." (PMID 30952903, 2019). "In overall, we demonstrated the potential of Skp2 targeting in prostate cancer treatment." (PMID 30952903, 2019). "Further research will be directed at the synthetic lethal interaction of RB loss with Skp2 overexpression in castration-resistant prostate cancer and targeting of Skp2 by combination of Bortezomib and FKB or its derivatives for treatment of RB deficient, castration resistant prostate cancer." (PMID 30885218, 2019). "Since FKB targets Skp2 degradation for its growth inhibitory effect on prostate cancer cell lines, we examined whether the anti-prostate cancer effects of MG132 or Bortezomib could be enhanced via combination with FKB." (PMID 30885218, 2019). "Given our recent findings that FKA inhibits prostate cancer by degrading Skp2, we aimed to evaluate whether FKA has a therapeutic role in osteosarcoma by suppressing Skp2." (PMID 30250282, 2018). "Moreover, forced upregulation of SKP2 promotes prostate cancer cell growth and tumorigenesis in a xenograft model, and overexpression of SKP2 in the mouse prostate leads to prostate intraepithelial neoplasia (PIN)." (PMID 25537506, 2015). "Furthermore, we showed that the elevations of Skp2 and H3K4me3 contributed to castration-resistant prostate cancer (CRPC) in mice, and were positively correlated in human PCa specimens." (PMID 25596733, 2015). "We next examined the effect of FKA on Skp2 expression in prostate cancer cell lines." (PMID 26497688, 2015). "We therefore examined whether Skp2 is a potential target responsible for FKA's growth inhibitory effect in prostate cancer cells." (PMID 26497688, 2015). "Skp2 is overexpressed in a wide range of cancers including prostate cancer." (PMID 26317998, 2015). "This study could benefit patients with castration resistant prostate cancer by targeting Skp2, Cdk2, and cyclin A using androgen treatment." (PMID 25271736, 2014). "Moreover, it has been reported that Skp2 inactivation promotes the senescence of prostate cancer cells." (PMID 25015320, 2014). "Prostate cancers typically display an inverse correlation between the levels of p27 and SKP2." (PMID 21182779, 2010).
prostate carcinoma (continued). "In order to mimic the situation prevailing in primary prostate cancers, we created the LNCaP derivative cell line, LNCaP-S14, which stably overexpresses Myc-tagged SKP2 at six to eightfold excess over endogenous SKP2, a manoeuvre that led to maximal downregulation of p27." (PMID 21182779, 2010). "In contrast, the commonly used human prostate cancer cell line LNCaP, despite faithfully recapitulating many features of human prostate cancer, expresses relatively high levels of p27 but low levels of SKP2 when compared to HeLa cells." (PMID 21182779, 2010). "In addition, our own data have shown that SKP2 overexpression in LNCaP prostate cancer cells is sufficient to direct p27 ubiquitylation and degradation." (PMID 21182779, 2010). "Indeed, elevated Skp2 expression is frequently observed in many tumors including breast and prostate carcinomas." (PMID 19549334, 2009). "Skp2 may be a potential therapeutic target for drug-resistant prostate cancer." (PMID 34068643, 2021). "Both Skp2 and p27 play vital roles in mediating the migration, proliferation and invasion of tumor cells as well as balancing immune tolerance in the development of autoimmune diseases, while 1,25-(OH)2D3 is reported to reduce Skp2 protein expression in metastatic prostate cancer cells." (PMID 31823770, 2019). "Overexpression of Skp2 partially rescued the growth inhibition induced by triol, indicating that other pathways or mechanisms, such as LXR signaling or cytoskeletal signaling, were probably involved in the growth inhibition caused by triol in prostate cancer cells." (PMID 23785446, 2013). "In prostate cancer, E2F2 activated CIT expression through the Skp2‐p27 axis and conducted androgen deprivation therapy resistance." (PMID 39999286, 2025). "Small-molecule inhibitors targeting SKP2, such as Brusatol, disrupt SCF complex assembly to restore p27 levels, demonstrating efficacy in preclinical models of lung and prostate cancers." (PMID 40534867, 2025). "The tumor suppressor features of miRNA-642 was also confirmed by an alteration of expression of potential target genes, such as WT1, NUAK1, RASSF3, SKP2, GPS2 and IGFBP3, in prostate cancer." (PMID 37108073, 2023). "Skp2 is a transcriptional target of STAT3, which, along with downstream genes (including RhoA), can stimulate prostate cancer metastasis and proliferation." (PMID 28157698, 2017). "FOXP3 was found to inhibit tumor cell growth, serving as an important repressor for breast cancer oncogene SKP2 and HER2, and FOXP3–miR-146–NF-kB Axis has been suggested in leading to apoptosis during tumor initiation and tumor suppression in prostate cancer." (PMID 28903735, 2017). "Skp2 is overexpressed in 86.4 % (64 of 74 samples) of pre-malignant HG-PIN and in 557 of 622 (89.2%) of primary prostate cancer specimens." (PMID 26497688, 2015). "In order to unveil the role of Skp2 in the turnover of DAB2IP protein, both prostate cell lines and prostate cancer specimens with a variety of molecular and cell biologic techniques were employed." (PMID 25115390, 2014). "First, FOXP3 represses expression of the HER2, Skp2, SATB1 and MYC oncogenes, and induces expression of the tumor suppressor genes p21 and LATS2 in breast and prostate cancer cells." (PMID 24406338, 2014). "Because overexpression of Skp2 did not completely reverse the growth inhibitory effects, we hypothesized that other additional pathways or mechanisms may be influenced by triol to cause cell growth inhibition of prostate cancer cells." (PMID 23785446, 2013). "Nevertheless, the reason for Skp2 down-regulation through mir-34 has not been completely investigated yet in human renal carcinoma cells and prostate cancer." (PMID 38559562, 2024).